DRC2 (dynein regulatory complex subunit 2)
Description:
Component of the nexin-dynein regulatory complex (N-DRC), a key regulator of ciliary/flagellar motility which maintains the alignment and integrity of the distal axoneme and regulates microtubule sliding in motile axonemes (By similarity). Plays a critical role in the assembly of N-DRC and also stabilizes the assembly of multiple inner dynein arms and radial spokes. Coassembles with DRC1 to form a central scaffold needed for assembly of the N-DRC and its attachment to the outer doublet microtubules.
Synonyms: CCDC65; NYD-SP28; FLJ35732; FAP250; CFAP250; CILD27
Tractability: Small molecule: a structure with a bound ligand is known.
Gene: Protein-coding gene on chromosome 12 (48,904,110 to 48,931,840, forward strand). Ensembl gene ENSG00000139537.
Subcellular location: Cytoplasm, cytoskeleton, flagellum basal body; Cell projection, cilium, flagellum; Cytoplasm, cytoskeleton, flagellum axoneme
Subcellular location (Human Protein Atlas): Centriolar satellite; Primary cilium transition zone; Vesicles; Annulus; Mid piece; Principal piece
Gene Ontology:
Molecular function: protein binding
Biological process: cilium assembly; regulation of cilium movement; axonemal dynein complex assembly; cilium movement; cilium-dependent cell motility; flagellated sperm motility
Cellular component: ciliary basal body; axonemal nexin link; axoneme; axonemal dynein complex; motile cilium
Genetic constraint (gnomAD): Loss-of-function variants: 39 observed, 50.76 expected, observed/expected ratio (o/e) 0.77, 90% interval 0.59 to 1. The upper end of that interval is the gene's LOEUF score, 1, which puts it in group 4 of 6, group 1 being the genes least tolerant of losing a copy. Missense variants: 484 observed, 550.92 expected, observed/expected ratio (o/e) 0.88, 90% interval 0.81 to 0.95. Synonymous variants: 175 observed, 200.19 expected, observed/expected ratio (o/e) 0.87, 90% interval 0.77 to 0.99.
Gene-disease validity (ClinGen):
ClinGen rates the evidence that DRC2 causes each of these diseases.
primary ciliary dyskinesia 27 (autosomal recessive): Definitive.
Homologues: Orthologues: macaque CCDC65 (98% identical), chimpanzee CCDC65 (97% identical), pig CCDC65 (86% identical), dog CCDC65 (86% identical), guinea pig CCDC65 (83% identical), rat Ccdc65 (81% identical), mouse Ccdc65 (81% identical), tropical clawed frog ccdc65 (61% identical), rabbit CCDC65 (51% identical), zebrafish ccdc65 (41% identical), Drosophila melanogaster CG30259 (26% identical). Paralogues in human: DRC1 (19% identical).
Diseases named in the same sentence as DRC2 in open-access papers:
DRC2 is named in the same sentence as 29 diseases in open-access papers, as found by Europe PMC text mining. Sharing a sentence is not in itself a finding about the gene and the disease. The quoted sentences say what the papers report.
primary ciliary dyskinesia (7 papers, 2013 to 2025). A rare, genetically heterogeneous, primarily respiratory disorder characterized by chronic upper and lower respiratory tract disease. "Specifically, mutations in DRC1, DRC2/CCDC65, and DRC4/GAS8 are associated with ciliary motility disorders, leading to primary ciliary dyskinesia (PCD)." (PMID 41460250, 2025).
ciliopathies (5 papers, 2021 to 2025). "In summary, scaffold proteins (DRC1, DRC2, DRC4) play a vital role in assembling the N-DRC since any defect in these subunits can cause severe ciliopathies." (PMID 37714832, 2023).
Hydrocephalus (2 papers, 2022 to 2025). Hydrocephalus is an active distension of the ventricular system of the brain resulting from inadequate passage of CSF from its point of production within the cerebral ventricles to its point of absorption into the systemic circulation. "Their defects cause situs inversus, hydrocephalus, and male infertility, emphasizing the importance of DRC1 and DRC2 for N-DRC assembly onto the ciliary axoneme and proposing an N-DRC assembly model." (PMID 40089458, 2025).
situs inversus (1 paper, 2025). A congenital condition in which there is complete right-to-left reversal of the position of the major thoracic and abdominal organs (that is, they are arranged in a mirror image of the normal positioning). "As PCD-related genes, Drc1−/−, Drc2−/−, and Drc4−/− mice also exhibited situs inversus, which implicates nodal cilia." (PMID 40089458, 2025). "Additionally, a small percentage of Drc1−/−, Drc2−/− and Drc4−/− mice exhibited situs inversus." (PMID 40089458, 2025).
DRC2 also shares sentences with these, for which no sentence is quoted: gastric cancer (3 papers); tumor (3); cancer (2); genetic disease (2); lung carcinoma (2); lymph node metastasis (2); adenocarcinoma (1); Airway obstruction (1); Bardet-Biedl syndrome (1); bronchitis (1); developmental delay (1); hepatocellular carcinoma (1); infectious disease (1); Joubert syndrome (1); Leukoencephalopathy (1); lung adenocarcinoma (1); lung adenoma (1); male infertility (1); neonatal respiratory distress syndrome (1); otitis (1); respiratory failure (1); sinusitis (1); uterine disease (1); Walker Warburg syndrome (1); Zellweger syndrome (1).